VHL (von Hippel-Lindau tumor suppressor)
Diseases named in the same sentence as VHL in open-access papers (continued):
Sharing a sentence is not in itself a finding about the gene and the disease.
von Hippel-Lindau disease (continued). "Patients with VHL syndrome inherit a single mutant VHL allele from a parent and develop the disease when the second wild-type copy is deactivated or lost." (PMID 31620170, 2019). "Von Hippel-Lindau (VHL) syndrome is a familial autosomal dominant hereditary neoplastic disease caused by mutations in the VHL gene." (PMID 31823746, 2019). "Here, we reported 2 cases in which patients had clinical phenotypes like those of VHL syndrome, which was further confirmed by finding a novel mutation site in the VHL gene of the patients via gene sequence analysis." (PMID 31823746, 2019). "There is evidence that mTOR inhibitors should be the favored immunosuppressant in patients with loss of VHL function and has been used in transplantation of patients with Von Hippel Lindau disease." (PMID 30326848, 2018). "Hypoxic signaling is also disrupted by loss-of-function mutations in VHL, which cause von Hippel-Lindau disease, a syndrome characterized by tumors in several organs, including kidney, central nervous system, pancreas and adrenal gland." (PMID 29768630, 2018). "von Hippel–Lindau disease is caused by mutations in the VHL tumor-suppressor gene, located on chromosome 3p25-26." (PMID 29479523, 2018). "Most patients with VHL syndrome inherit a germline mutation of the VHL gene from affected parents and a wild-type gene from the unaffected parent." (PMID 28785532, 2017). "Von Hippel-Lindau (VHL) syndrome is an autosomal-dominant, multi-organ, familial neoplastic syndrome, which is caused by genetic aberrations of the tumor suppressor gene VHL." (PMID 28785532, 2017). "Many tumor types, such as RCC, and those tumors associated with von-Hippel Lindau (VHL) syndrome create “pseudohypoxia” via inactivating mutations of the VHL protein that would normally ubiquitinate HIF-1α." (PMID 26934654, 2016). "von Hippel–Lindau disease (VHL) is an autosomal dominant inherited genetic disorder caused by a germline mutation of chromosome 3 (VHL gene)." (PMID 27446927, 2016). "Mutations of the VHL gene are associated with Von Hippel-Lindau disease, which is a hereditary cancer syndrome caused by germline mutations in the VHL tumor suppressor gene." (PMID 27107416, 2016). "The most well-known CRL2 substrate recognition receptor is the tumor suppressor protein VHL that is mutated in von Hippel–Lindau (VHL) syndrome, a rare hereditary cancer syndrome." (PMID 27222660, 2016). "Von Hippel–Lindau (VHL) syndrome is a dominantly inherited multisystem cancer syndrome caused by a heterozygous mutation in the VHL tumor suppressor gene." (PMID 27527340, 2016). "von Hippel–Lindau disease is an autosomal-dominant hereditary cancer syndrome involving a germline mutation in VHL." (PMID 27047799, 2016). "Von Hippel-Lindau disease (VHL) is an autosomal dominant systemic syndrome that results from a mutation in the VHL gene on chromosome 3 (3p25-26)." (PMID 25885645, 2015). "Mutations of pVHL are related to a pathological outcome termed VHL syndrome, an inherited form of cancer." (PMID 24886840, 2014). "von Hippel-Lindau syndrome is an autosomal-dominant disorder, and mutation of one copy of the VHL tumor suppressor gene is associated with the development of the tumors." (PMID 24678933, 2014). "Mutation in VHL gene is associated with Von Hippel-Lindau disease, which exhibits severe malignant tumors." (PMID 23776465, 2013). "von Hippel-Lindau disease is caused by germ-line mutations in the VHL tumor suppressor gene located on the short arm of chromosome 3 (3p25-26)." (PMID 22799452, 2012). "A total of 289 probands suspected of having VHL syndrome have been screened for mutations in the VHL gene." (PMID 22799452, 2012). "Germline mutations of VHL have been reported in patients with the von Hippel-Lindau disease, a familial cancer syndrome." (PMID 23127113, 2012).
von Hippel-Lindau disease (continued). "UBP33 (encoded by USP33/VDU1) and UBP20 (encoded by USP20/VDU2) are 59% identical USP-type DUBs that interact with the tumor suppressor E3 ubiquitin ligase VHL (pVHL), mutations in which are associated with von Hippel-Lindau disease." (PMID 19007433, 2008). "The β-domain of VHL is the region of the protein that harbors the naturally occurring mutations found in von Hippel-Lindau disease." (PMID 19007433, 2008). "Therefore, when only one tumor other than RCC is present, the VEF requires additional evidence to support an association between a VHL variant and VHL syndrome." (PMID 40647474, 2025). "In the below cases, we describe a new clinical entity we call “Incidental Von Hippel Lindau Disease” in 6 otherwise healthy patients who pursued genetic screening with low a priori risk for VHL (5 individuals pursuing testing for hereditary breast cancer risk and 1 to determine ancestry)." (PMID 40063608, 2025). "The von Hippel-Lindau (VHL) syndrome is a rare autosomal dominant disorder caused by mutations in the VHL tumor suppressor gene, leading to the development of benign and malignant tumors in multiple organs, including the kidneys, brain, spine, retina, and pancreas." (PMID 40937003, 2025). "Nearly 100% of the individuals with VHL syndrome are expected to be symptomatic by the age of 65 years, but some germline VHL variants may be associated with lower penetrance." (PMID 40647474, 2025). "The presence of these tumors in a patient with a germline VHL variant could lead to inaccurate attribution of these tumors to the germline variant and VHL syndrome." (PMID 40647474, 2025). "Von Hippel–Lindau disease (VHL) is caused by germline mutations of the VHL gene." (PMID 41302074, 2025). "VHL is a tumor suppressor gene whose mutation is associated with an autosomal dominant disease named von Hippel–Lindau syndrome that results in the development of retinal hemangioblastomas, central nervous system (CNS) hemangioblastomas, PPGLs, and renal carcinomas." (PMID 39000254, 2024). "Also, 9% of the cases are associated with Von Hippel-Lindau syndrome - VHL (VHL gene), 5% corresponds to multiple endocrine neoplasia 2 syndrome—MEN2 (RET proto-oncogene), and 2% are associated with neurofibromatosis type 1 syndrome—NF1 (NF1 gene)." (PMID 36685941, 2022). "Meanwhile, the mutation of VHL p.Arg167Gln is the only pathogenic mutation leading to VHL syndrome." (PMID 34923986, 2021). "In more recent times, seven families with erythrocytosis and one large family with von Hippel-Lindau disease have been described with mutations in a VHL cryptic exon, which produced dysregulation of VHL splicing associated with downregulation of VHL protein expression." (PMID 34440325, 2021). "An increased level of genetic homogeneity was observed among clear-cell RCC (CCRCCs) with germline VHL mutations, compared to sporadic CCRCCs; this greater homogeneity reflects the smaller number of copy number alterations occurring in VHL syndrome-associated CCRCCs." (PMID 32751108, 2020). "Von Hippel–Lindau (VHL) syndrome is associated with pheochromocytomas, paragangliomas and pancreatic neoplasia, and is caused by the loss of the VHL tumour suppressor gene, regulating the hypoxia-inducible factor (HIF) and vascular endothelial growth factor (VEGF) pathways." (PMID 31443481, 2019). "Germline mutations in the VHL gene cause the von Hippel-Lindau syndrome (VHL disease)." (PMID 30925729, 2019). "Besides, the training set that annotates “VHL” (Von Hippel-Lindau disease) as a disease entity confuses the models because VHL is also used as a gene name, since the mutation of this gene causes VHL disease." (PMID 31138109, 2019).
von Hippel-Lindau disease (continued). "In addition, the incidental finding of a nonsense mutation in VHL is especially interesting, since it predisposes for Von Hippel-Lindau (VHL) syndrome in an autosomal dominant manner." (PMID 28526081, 2017). "Von Hippel–Lindau disease is caused by mutations in the gene encoding the VHL protein (pVHL)." (PMID 25605410, 2015). "Summing up, VHL gene is a key factor, mostly because of the following reasons: (a) it often predisposes patients with VHL syndrome to develop hereditary ccRCC; (b) it is the most common alteration in sporadic ccRCC; and (c) it is found even in small ccRCCs at early diagnosis." (PMID 25120953, 2014). "Kidney cancers are mostly of sporadic origin, but some patients are genetically predisposed, suffering from von Hippel-Lindau (VHL) syndrome, which is connected with the loss of the VHL suppressor gene function (VHL follows an autosomal dominant hereditary pattern)." (PMID 25120953, 2014). "Von Hippel-Lindau (VHL) syndrome is a hereditary condition predisposing to the development of different cancer forms, related to germline inactivation of the homonymous tumor suppressor pVHL." (PMID 24886840, 2014). "Mutations of the VHL gene are associated with Von Hippel–Lindau disease." (PMID 23825632, 2013). "Von Hippel-Lindau disease (VHL) is a rare hereditary neoplastic disorder caused by germline mutations in the VHL gene, leading to the development of tumors in several organs, including the central nervous system, pancreas, kidneys, and reproductive organs." (PMID 40796357, 2025). "Von Hippel-Lindau disease (VHL) is a multisystem cancer syndrome caused by the inactivation of the VHL tumor suppressor gene and involves various organ systems including the central nervous system (CNS), endocrine system, and the kidneys." (PMID 37555195, 2023). "Likewise, the most common hereditary RCC appears in patients with a mutation in the VHL gene (located in chromosome 3p), causing the von Hippel-Lindau disease (VHL) (ORPHA:892), with a predisposition to present ccRCC, due to the role of the VHL gene as a tumor suppressor." (PMID 35813211, 2022). "Von Hippel-Lindau disease (VHL) is an autosomal dominantly inherited tumor syndrome that is caused by heterozygous inactivating mutations of the VHL tumor suppressor gene, usually in the germline." (PMID 31673890, 2020). "Von Hippel–Lindau disease is rare, the size of this cohort is relatively small, and the follow-up durations are not sufficiently long, which may influence the correlation analysis between the frequent mutations in the VHL gene and the clinical phenotypes." (PMID 31620170, 2019). "Studies have indicated that about 20% of the individuals with VHL syndrome have post-zygotic de novo alterations, and an estimated 5% of the individuals with VHL have somatic mosaicism." (PMID 40647474, 2025). "The probe mix contains probes targeting each VHL exon, genes located close to VHL, and references for detecting sequences on other chromosomes specifically designed to diagnose the Von Hippel–Lindau syndrome." (PMID 41302074, 2025). "Von Hippel–Lindau syndrome (VHL, OMIM # 193300) is a rare, autosomal dominant hereditary cancer syndrome caused by the heterozygous germline pathogenic variants in the VHL gene." (PMID 40647474, 2025). "VHL differential disorders: Alterations in several genes can result in genetic conditions with clinical features resembling those in VHL syndrome." (PMID 40647474, 2025). "Among the P/LP germline VHL variants, 69% (20/29) were INT2GRATE Positive, consistent with the patients’ classic VHL syndrome and the actionability of these germline variants." (PMID 40647474, 2025). "In fact, VHL-related PPGLs have a low rate of metastatic potential; patients with familial pheochromocytomas in VHL syndrome were found to have metastatic or locally aggressive tumors in 8% of cases." (PMID 39000254, 2024).
von Hippel-Lindau disease (continued). "In the context of the VHL syndrome, biallelic VHL inactivation in cells is thought to mimic the effect of hypoxia." (PMID 39336783, 2024). "The VHL syndrome was excluded via VHL gene sequencing in fifteen patients with a median age of 32 years (range: 13–51 years), who only exhibited unilateral solitary RH and had a negative family history." (PMID 39336783, 2024). "Germline mutations such as multiple endocrine neoplasia type 1 (MEN1), von Hippel–Lindau syndrome (VHL), neurofibromatosis type 1 (NF1), and the occasionally tuberous sclerosis complex (TSC) are the most identified PNET-associated mutations." (PMID 38279330, 2024). "Two patients were carriers of MEN1 (Multiple Endocrine Neoplasia Type 1) and one patient of VHL (Von Hippel-Lindau disease)." (PMID 36358607, 2022). "Approximately 10% of p-NETs are due to an inherited syndrome, which includes multiple endocrine neoplasia type 1 (MEN1), von Hippel-Lindau disease (VHL), neurofibromatosis type 1 (NF1), and tuberous sclerosis complex (TSC)." (PMID 35053593, 2022). "The discovery of the VHL gene stemmed from VHL syndrome (von Hippel-Lindau syndrome), which is an autosomal dominant hereditary disease." (PMID 35448166, 2022). "In 1993, the von Hippel–Lindau gene (VHL) was discovered in a patient with von Hippel–Lindau disease with RCC." (PMID 34575959, 2021). "von Hippel-Lindau syndrome is caused by mutations of the VHL tumor suppressor gene and the subsequent loss of its native protein product, pVHL." (PMID 35111762, 2021). "In this case, testing of SDHx genes is recommended as a first test, while testing of the VHL gene is recommended only in case of other specific manifestations of the disease or the presence of von Hippel–Lindau syndrome in the family." (PMID 34439371, 2021). "Other well-known hereditary syndromes associated with PGL/PCC include multiple endocrine neoplasm type 2 (MEN2), von Hippel-Lindau disease (VHL) and neurofibromatosis type 1 (NF1)." (PMID 33308260, 2020). "von Hippel-Lindau syndrome (VHLS) is a rare, autosomal dominant genetic disease with high penetrance and variable phenotypic expression caused by variants in the VHL gene." (PMID 32117777, 2020). "We reported two cases in which a novel mutation site in the c530-536delGACTGGA region in exon 3 of the VHL gene resulted in the development of VHL syndrome." (PMID 31823746, 2019). "Note, gene losses at VHL locus favoring less malignant tumour progression are further supported by observations made in von-Hippel-Lindau disease." (PMID 28486536, 2017). "We chose to study two forms of hereditary kidney cancer, i.e., von Hippel-Lindau disease (VHL) and Tuberous Sclerosis Complex (TSC), due to germline mutations of VHL or TSC1/2, respectively." (PMID 27682873, 2017). "Of which, VHL (Von Hippel-Lindau syndrome) is a tumor suppressor and expressed significantly lower in edit+ primary samples than in edit- samples (P = 3.78e−02, t-test)." (PMID 28009993, 2017). "With advances in understanding the molecular biology of VHL syndrome, several therapies targeting downstream targets of VHL, such as VEGF, are currently available in treating patients with common manifestations such as RCC." (PMID 28785532, 2017). "In 1995, the Clinical Research Group for VHL in Japan reviewed data from Japan and reported that 9% of the evaluated patients had type 2 VHL syndrome." (PMID 27527340, 2016). "It includes all major pVHL functions and is able to credibly reproduce VHL syndrome at the molecular level." (PMID 24886840, 2014). "The largest number of concurrent CVs was observed in the VHL gene (von Hippel-Lindau syndrome, MIM# 193300), followed by BRCA1/BRCA2 (hereditary breast cancer syndrome, MIM# 113705, 600185)." (PMID 18974781, 2008). "The von Hippel-Lindau (VHL) gene is a tumor suppressor gene predisposing to both sporadic clear-cell (conventional) RCC and von Hippel-Lindau disease." (PMID 15932632, 2005).
von Hippel-Lindau disease (continued). "In addition, we identify mutations in rare genetic diseases that alter 5' UTR length, including a deletion in the VHL 5' UTR in von Hippel-Lindau disease that shifts translation toward the shorter VHLp19 isoform." (PMID 41974896, 2026). "Among the 29 patients with pathogenic/likely pathogenic VHL variants, 26% did not exhibit VHL personal features and/or tumors, and 45% were negative for a family history of VHL syndrome." (PMID 40647474, 2025). "Variants VHL:c.562C>G (p.Leu188Val), VHL: c.429C>T (p.Asp143=), and VHL:c.388G>A (p.Val130Ile) have been reported in association with erythrocytosis and not VHL syndrome." (PMID 40647474, 2025). "The variants VHL: c.429C>T (p.Asp143=) and VHL:c.388G>A (p.Val130Ile) have also been reported in individuals with erythrocytosis and not VHL syndrome." (PMID 40647474, 2025). "An agnostic approach was used in this study to select patients based on their VHL variant status rather than their personal history of VHL syndrome, thereby reducing potential ascertainment bias." (PMID 40647474, 2025). "RH tends to occur either sporadically or as a subset of central nervous system (CNS) hemangioblastoma in the Von Hippel–Lindau (VHL) syndrome (OMIM #193300), an inherited autosomal dominant disorder caused by mutations in the VHL tumor suppressor gene (VHL, OMIM#608537)." (PMID 39336783, 2024). "Since the von Hippel–Lindau (VHL) disease tumor suppressor gene VHL was identified in 1993 as the genetic basis for a rare disorder, the von Hippel–Lindau (VHL) syndrome (OMIM 193300) has been an autosomal dominant hereditary condition characterized by a predisposition to tumors." (PMID 39201746, 2024). "A possibility supported by experimental data from BioGRID could be that the Myc‐fibronectin interaction would be indirect, passing through the von Hippel–Lindau disease tumour suppressor (VHL), which is in the cytoplasm, membrane and nucleus, simultaneously." (PMID 37415307, 2023). "The dysregulation of the pVHL protein is related to VHL (Hippel–Lindau syndrome) disease." (PMID 35508480, 2022). "Furthermore, RSUME suppresses ubiquitin conjugation to hypoxia-inducible factor (HIF) by blocking VHL E3-ubiquitin ligase activity, contributing to the development of von Hippel-Lindau disease." (PMID 35528020, 2022). "In non-cancerous conditions such as the von-Hippel-Lindau-syndrome, mutated vHL protein also causes angiogenesis-dependent tumors including haemangioblastomas, a tumor arising from blood vessel in the central nervous system." (PMID 32397610, 2020). "Key syndromes include multiple endocrine neoplasia type 1 (MEN1), von Hippel–Lindau disease (VHL), neurofibromatosis type 1 (NF1), and tuberous sclerosis complex (TSC), which are characterized by germline mutations in the tumor-suppressor genes MEN1, VHL, NF1, and TSC1 or TSC2, respectively." (PMID 32850899, 2020). "ccRCC is also one of the most common manifestations of von Hippel Lindau (VHL) syndrome, where inactivation of the pVHL tumor suppressor, a component of the E3 ubiquitin ligase complex targeting HIF-1α for degradation, leads to development of lethal ccRCC in patients." (PMID 26211615, 2015). "In our case, since there was no mutation of the VHL gene in the patient’s family, suggestive of von Hippel-Lindau syndrome, we suspect that the patient had a de novo mutation of the gene." (PMID 24678933, 2014). "In the case of von Hippel-Lindau disease, small molecule activators of mutant VHL may be able to sustain HIFα degradation and prevent tumour angiogenesis." (PMID 18047733, 2007). "The disease associations in OMIM for these genes also revealed that 38% were hereditary cancer predisposition syndromes (e.g., VHL associated with von Hippel-Lindau syndrome) and 62% were not known to include cancer as a predominant feature (e.g., FGFR3 associated with Achondroplasia)." (PMID 39761285, 2025).